TLR4 (toll like receptor 4)
Diseases named in the same sentence as TLR4 in open-access papers (continued):
Sharing a sentence is not in itself a finding about the gene and the disease.
infection (continued). "TBK1 plays a critical role as an integrator and inducer of RIG-I–MAVS, cGAS–STING, and TLR4–TRIF signaling pathways in response to infection by RNA viruses, DNA viruses, and bacterial LPS, respectively." (PMID 30769920, 2019). "TLR4 is an important mediator of the inflammatory response to infection and plays a role in the development and progression of HCC." (PMID 31068809, 2019). "The comparison between WT and TLR4−/− macrophages revealed decreased levels of the Arg1 and Nos2 transcripts throughout the course of infection (respectively)." (PMID 30555476, 2018). "Infection of TLR4 knockout mice with IAV resulted in a variety of outcomes, possibly due to variations in the genetic background of the mouse strains and the use of different experimental systems, including the analyzed time points." (PMID 30571771, 2018). "Using a mouse infection system displaying severe MiP outcomes, we found that the expressions of TLR4 and IFNAR1 in the maternal compartment take part in deleterious MiP outcomes, but their fetal counterparts patently counteract these effects." (PMID 29440369, 2018). "There are numerous studies showing a higher expression of TLR4 during the postpartum period and infection in Holstein cattle." (PMID 29642663, 2018). "We chose this infection model to unravel the impact of the fetus-derived innate immunity receptors TLR4 and IFNAR1 on severe outcomes of MiP." (PMID 29440369, 2018). "One of the major pathways regulating the production of most cytokines after infection, injury or stress is the TLR4 pathway." (PMID 30174579, 2018). "Our results agree with the results of previous studies showing that LPS-induced TLR4 signaling stimulates the synthesis of pyrogenic cytokines at the site of infection including the brain." (PMID 29854828, 2018). "In this regard, it is interesting that previous data showed that in HIV patients there is an infection of Kupffer cells in the liver which enhanced LPS cell-surface receptors (TLR4) and increased IL-6 and TNF-a expression." (PMID 29434676, 2018). "We observed increased numbers of infected macrophages during the course of infection in TLR4−/− macrophages, and an increased rate only after 48 h of infection of TLR2−/− macrophages." (PMID 30555476, 2018). "Transcriptional levels of neutrophil TLR2 and TLR4 at 3 h post-infection with SS2 ZY05719 were 2.9- and 2.5-fold that of untreated neutrophils, whereas that of TLR6 was unchanged." (PMID 30581435, 2018). "This low-inflammatory LPS is poorly recognized by the PRR Toll-Like-Receptor 4 (TLR4), making macrophages and neutrophils less able to control the infection." (PMID 30532257, 2018). "Louis, MO, USA) led a robust phosphorylated GSK3β and a moderately increased expression of TLR4 and MyD88 proteins but reduced the abundance of NF-κB and GSK3β proteins in U937-derived macrophage-like cells in response to the H37Rv infection." (PMID 30356420, 2018). "In the resting state, TLR4 has low expression level in the brain, although it can be elevated in some pathological conditions (infection and tissue damage)." (PMID 29382328, 2018). "Induction of PTGS2/COX-2 during infection is mediated by TLR4 and NFκB (nuclear factor kappa-light-chain-enhancer of activated B cells)." (PMID 29661181, 2018). "TLR4 mRNA expression at 2 h post-infection with SS2 ZY05719 was 2.8-fold that of blood cells from untreated mice." (PMID 30581435, 2018). "The results illustrated that TLR2, TLR4 and TLR9 were up-regulated by over 300% in HEC-1-A cell 24 h post-infection (p.i.), and only TLR4 transcription was enhanced by over 700% in VK2 cells." (PMID 30419930, 2018). "Inhibition of Notch signaling by γ-secretase inhibitor DAPT impairs TLR4-stimulated accumulation of NF-κB subunits p65 in the nucleus and subsequently reduces LPS- and infection-mediated IL-6 production." (PMID 30042932, 2018).
infection (continued). "The UdLAMPs of both Ureaplasma stimulated the gene expression of IL-1β, TNF-α, TLR2 and TLR4 after 6 and 12 h following infection in macrophages." (PMID 30050519, 2018). "By triggering TLR4- or RAGE-mediated multiple inflammatory pathways, S100A8/A9 plays an important role in protecting the body from pathogenic infection." (PMID 29942307, 2018). "There is a growing list of viruses that induce an inflammatory response during acute infection through TLR4 activation." (PMID 30571771, 2018). "Here, we reported the roles of TLR2, TLR4, and the adaptor molecule MyD88 in mediating the phagocytosis of L. amazonensis and conferring resistance to infection, in contrast to the higher infectivity index observed in the absence of those molecules." (PMID 30555476, 2018). "HMGB1 has also been recognized as a DAMP that elicits a TLR4-dependent cytokine storm when released from necrotic cells in response to injury, infection, or other inflammatory stimuli." (PMID 29535197, 2018). "To ascertain the role of fetal TLR4 in the response to infection, we used primary cultures of trophoblasts isolated from noninfected placentas with wild-type or Tlr4−/− genotypes." (PMID 29440369, 2018). "The reduction in fetal weight induced by infection was less pronounced in Tlr4−/− pregnant females than in wild-type pregnancies and was marginally recovered in Tlr4−/− pregnant females that carried fetuses expressing TLR4." (PMID 29440369, 2018). "The finding that ICAM1 is upregulated in wild type, but not in TLR4−/− eyes, correlates with our previous findings that neutrophil recruitment is decreased in TLR4−/− eyes following infection." (PMID 29661181, 2018). "TLR4 is activated following recognition of microbial peptides (such as LPS) after infection or endogenous molecules (HMGB1, heat shock proteins, ATP) that are released after cellular damage or psychological stress." (PMID 30174579, 2018). "The baseline level of C23 expression was slightly higher than that of TLR4, but both TLR4 and C23 protein expression were up-regulated from 1 h pi to 4 h pi, which is during the early stage of infection." (PMID 29427996, 2018). "Using a transcriptomics approach, we identified 15 proinflammatory and immunomodulatory TLR4-dependent genes whose expression was increased 5-fold or greater specifically in the retinas of eyes 4 h after infection with B. cereus." (PMID 29661181, 2018). "TLR4, the most studied TLR, has evolved as the receptor that responds to pathogenic infections, specifically via interaction with lipopolysaccharide (LPS), a potent endotoxin of Gram-negative bacteria." (PMID 29636723, 2018). "In vivo studies confirmed the critical role that TLR2 and TLR4 play in infection-induced peritoneal inflammation and fibrosis." (PMID 30538643, 2018). "Toll‐like receptor 4 (TLR4) mediates both infection‐induced and sterile inflammation by recognizing pathogen‐associated molecular patterns and endogenous molecules, respectively." (PMID 28776958, 2017). "By contrast, leptospires would not need to escape the recognition by NOD1 in humans because they avoid TLR4 recognition of their atypical LPS, potentially resulting in severe infection." (PMID 29211798, 2017). "At the same time, the infection process activates a variety of host innate immune responses, including the TLR4 signaling pathway, to induce an antiviral state." (PMID 28421060, 2017). "We found that the increase in activation/differentiation following EBOV-mediated stimulation of TLR4 resulted in a significantly increased rate of infection of monocytes." (PMID 28542576, 2017). "Siglec-9 helps endocytosis of toll-like receptor 4, regulates macrophages polarization, and inhibits the function of neutrophils during infection." (PMID 29209331, 2017). "Infection of TLR4-KO macrophages led to a remarkable reduction of ATF4 nuclear translocation when compared with infected wild-type cells." (PMID 29213084, 2017).
infection (continued). "Since TLR2 and TLR4 are involved in the recognition of Leishmania by neutrophils, it is meaningful that infection with L. major promotes CD14 internalization in neutrophils." (PMID 28187163, 2017). "Gene expression analysis in TIFAB knockout HSPCs revealed the upregulation of immune and infection response signatures, which suggests hypersensititivy to TLR4 stimulation." (PMID 29181334, 2017). "We next determined the relative rates of infection of THP-1 cells following TLR4-mediated differentiation." (PMID 28542576, 2017). "After infection with T. gondii, a lower Ifngr1 mRNA and a higher expression of Tlr4 mRNA were observed in Nox4−/− BMDMs." (PMID 28743960, 2017). "To assess if monocyte/macrophage subsets were activated during infection, we examined the expression of Toll-like-receptor-4 (TLR-4) on these subsets." (PMID 28874759, 2017). "During Schistosoma japonicum infection, TLR2 and TLR4 promoted opposite adaptive immune responses, including T cell activation and cytotoxic gene expression, which led to different infection outcomes." (PMID 28784165, 2017). "TLR4 plays a well-established regulatory role in the innate immune response to infection and in adaptive responses consenting probiotic bacteria colonization." (PMID 28642706, 2017). "When leptospires in contaminated water infect an animal host via cut or abraded skin, such antagonistic activity will cause multiple other LPS-containing pathogenic species in the wound to become inert with respect to TLR4 stimulation during early infection." (PMID 28536433, 2017). "Through TLR4, platelets act as inflammatory sentinels that surround and isolate an infection but modulate pro-inflammatory cytokine release." (PMID 28976997, 2017). "In our DENV infection model, morbidity and mortality were both somewhat delayed in Ifnar-/-x Tlr4-/- B6 mice, though mice succumbed to infection at the same rates." (PMID 29121099, 2017). "In cattle, mRNA levels of TLR2 and TLR4 were increased following infection of bovine intestinal epithelial cells with C. parvum, whereas the expression of TLR1, TLR3 and TLR5-TLR10 were unchanged." (PMID 28800747, 2017). "Taken together, Siglec-E plays a novel role in controlling the septic response with TLR4 and helps to maintain a healthy cytokine balance following infection." (PMID 29209331, 2017). "Siglec-9 helps endocytosis of TLR4, regulates macrophages polarization, and inhibits the function of neutrophils during infection." (PMID 29209331, 2017). "We observed maximum TLR4 expression at the earlier stages of infection, thereafter the levels though declined remained significant till 1 day p.i. in the spleen." (PMID 29142761, 2017). "F protein also causes toll-like receptor 4 (TLR-4) signaling with NF-κβ and IFN-inducible gene activation early in infection." (PMID 28267794, 2017). "Bovine MECs (bMECs) stimulated with E. coli or LPS revealed that NF-κB plays a vital role in E. coli- or LPS-induced infections through TLR4-induced inflammation." (PMID 26976286, 2016). "Despite the protective role of TLR4, a hypervirulent strain of M. tuberculosis recognized predominantly by this receptor was also found to induce high levels of type I IFN during infection, a cytokine that was associated with exacerbated disease." (PMID 27849167, 2016). "The pattern recognition receptor TLR4 is well known as a crucial receptor during infection and inflammation." (PMID 27670746, 2016). "Meanwhile, MyD88, LBP and TLR4 probably play an important role in stimulating immune and antigen presentation in piglet’s response to the infection of E. coli F18." (PMID 27809935, 2016). "We undertook this study in order to investigate the possible involvement of TLR4 in infection by M. leprae." (PMID 27458573, 2016). "We have found that TLR2 and TLR4 cooperate in the early control of this infection, while TLR9 is dispensable." (PMID 28119856, 2016).
infection (continued). "As expected, the TLR4 inhibitor entirely blocked the antiviral activity of LPS in human macrophages 24 h post-infection with HIV-1VSV, while leaving that of PolyI:C unaffected." (PMID 27310139, 2016). "TLR4 signalling can trigger the activation and recruitment of neutrophils and macrophages that can kill or limit the spread of infection at an early stage, allowing time for the adaptive immune response to develop." (PMID 27784777, 2016). "Blocking TLR4 signalling by either of these means potently inhibited C. trachomatis-induced PKR activation indicating a requirement for TLR4 in the induction of PKR activation in response to infection." (PMID 27021640, 2016). "The genes encoding CD14 (42.55 fold) and MyD88 (5.54 fold), two proteins involved in signaling trough TLR4, had increased expression levels during infection." (PMID 27982111, 2016). "Under LPS stimulation, over-expression TLR4 sheep rapidly activated the TLR4 signaling pathway and help the host launch an immune response against pathogen invasion and infection." (PMID 27408716, 2016). "Activation of TLR2 and TLR4 along the time course of the experimental infection triggered early intestinal (innate) immune response at 1 and 2 dpi." (PMID 26738723, 2016). "The highest TLR2 and TLR4 expression levels were at 2 dpi, decreasing during the time of infection and reaching a minimum at 30 dpi." (PMID 27511368, 2016). "At peak infection, mice consuming the RS and WB diets exhibited the highest expression (P = 0.040) of Tlr4 relative to CN diet treatment mice." (PMID 28031748, 2016). "Crucially, infection resulted in robust IRE1α RNAse activity that was dependent on TLR4 signalling and inhibition of IRE1α RNAse activity prevented PKR activation." (PMID 27021640, 2016). "During the initiation of infection, several macrophage receptors with specific binding sites, including TLR4, that interact directly with Brucella have been identified." (PMID 27098179, 2016). "Our data indicated that TLR4 signaling was activated in Pxr−/− mice after Lm infection, and the inflammation induced by TLR4 signaling was detrimental to host defense against the infection." (PMID 27550658, 2016). "In this study we have demonstrated that infection of monocyte-derived DC with C. trachomatis or stimulation with LPS results in TLR4-dependent activation of the IRE1α branch of the UPR, and that an inhibitor of IRE1α RNAse activity blocks PKR phosphorylation." (PMID 27021640, 2016). "There are many studies evaluating the relationship of CD14, TLR2, and TLR4 in various infections of adults." (PMID 27252945, 2016). "Altogether, our findings indicate that TLR4-dependent induction of type I IFN resulted in the induction of NO production by macrophages in response to BTB 02-171 infection." (PMID 27849167, 2016). "The bacterial load was significantly reduced by TLR2 or TLR4 activation before the infection (24 h p.i.: 19% or 12% reduction; 48 h p.i.: 39% or 60% reduction)." (PMID 27105429, 2016). "Although we demonstrated that TLR2 and TLR4 expression is regulated during E. chaffeensis infection, it is possible that other TLRs can also be regulated by the Notch signaling during infection." (PMID 27381289, 2016). "Generally, mice consuming the WB diets displayed lower expression of bacterial recognition genes (Tlr4, RegIIIγ), the defense cytokine gene Relmβ, the Th1 regulatory cytokine gene Ifnγ, and the regulatory cytokine gene Il-10 during peak and late infection." (PMID 28031748, 2016). "Lastly, we provided evidence that infection or LPS stimulation results in the activation of IRE1α that is also TLR4 dependent." (PMID 27021640, 2016). "Our recent findings support the explanations that infection of gastric epithelial cells with H. pylori induces TLR4/MD-2 expression, which contributes to the inflammatory response." (PMID 27667993, 2016).
infection (continued). "HCV-infection (NS5A protein) up-regulates TLR4 expression and pro-inflammatory cytokine production, making hepatocytes very sensitive to ethanol-induced LPS effects." (PMID 25664450, 2015). "TLR4-defective (C3H/HeJ) and wild-type (C3H/HeOuJ) mice were intranasally infected with adeno-mS100A9 or adeno null virus and examined 10 days post infection (as the kinetics of the C3H/HeOuJ response were slightly delayed compared with C57Bl/6 mice)." (PMID 25706559, 2015). "Gram-negative bacteria release LPS, which activates Toll-like-receptor-4 (TLR4) in the host, initiating an inflammatory response to infection." (PMID 26330186, 2015). "In the porcine intestinal epithelial IPEC-J2 cell line, the expression and the regulation of TLR4 after infection with an enteric virus has been reported." (PMID 25806034, 2015). "Our results suggest that TLR1 and TLR6 mediate the innate immune response to M. haemolytica while TLR2 and TLR4 mediate response to infection by IBR and other viruses." (PMID 26121276, 2015). "Because TLR signalling is involved in the activation and migration of NK cells during infection, we used MyD88−/− and TLR4−/− mice to assess the role of TLR signalling pathways in the recruitment of NK cells in our sterile injury model." (PMID 25609031, 2015). "In contrast, in the present study, TLR4 transcription was down regulated with infection and disease progression as well as other TLRs and cytokines." (PMID 26465878, 2015). "Levels of TLR4 are increased by heat shock proteins and various cellular factors produced during infection, while the ligand for TLR7 is ssRNA, of which the H5N1 genome is comprised." (PMID 26238195, 2015). "The increased expression of TLR2 and TLR4 by the Treg cells results in increased IL-10 which can play an immunotolerogenic role during the infection." (PMID 26635448, 2015). "The interaction between MMTV Env protein and Toll-like receptor 4 allows the infection of B cells, that present Sag (Super Antigen) to CD4+ T cells." (PMID 26214095, 2015). "Recent studies in rodents have demonstrated the efficacy of TLR4 agonists as immunomodulators in models of infection." (PMID 26640957, 2015). "In contrast, Tlr4 seemed to have a high level of steady state expression in the mock sample and was down regulated after infection." (PMID 25856589, 2015). "A recent study in mice has shown that infection with L. infantum resulted in the increased transcription of TLR2 and TLR4 and associated cytokines." (PMID 26465878, 2015). "Enhanced expression of TLR2 and TLR4 in response to infection has also been observed in another ovine infectious disease, Johne's disease, caused by Mycobacterium avium subspecies paratuberculosis (MAP)." (PMID 25124770, 2014). "TLR4 signaling is a critical activator of immune defense during infection, and the effective termination of TLR signaling is essential to prevent detrimental systemic effects, including septic shock." (PMID 25120616, 2014). "The involvement of TLR2 and TLR4 in C. trachomatis mediated infection response has been reported by earlier studies." (PMID 25123797, 2014). "We confirmed that C. jejuni primarily activates the innate receptors TLR2 and TLR4, and found that TLR4 signaling was responsible for most of the inflammatory changes seen during infection." (PMID 25033044, 2014). "We also found that the induction of the inflammatory and Th1/Th17 immune responses to infection in these mice depended on specific Toll-like receptors, principally TLR4, which we identified as the main driver of inflammation." (PMID 25033044, 2014). "A recent report also indicated the critical role of TLR4 in mediating innate response during primary infection of human lymphatic endothelial cells (LEC) and lytic replication of the latent Kaposi Sarcoma herpesvirus (KSHV)." (PMID 24722640, 2014). "Blocking of TLR2 (p = 0.0063) or TLR4 (p = 0.0047) prior to infection or stimulation with 19 kDa significantly increased epithelial pCREB production (p = 0.0163)." (PMID 24489729, 2014).